DDX56 (DEAD-box helicase 56)
Diseases named in the same sentence as DDX56 in open-access papers:
DDX56 is named in the same sentence as 30 diseases in open-access papers, as found by Europe PMC text mining. Sharing a sentence is not in itself a finding about the gene and the disease. The quoted sentences say what the papers report.
colorectal cancer (7 papers, 2020 to 2025). A primary or metastatic malignant neoplasm that affects the colon or rectum. "It has been shown that DDX56 dysregulation is associated with squamous cell lung carcinoma 8, glioblastoma 9, osteosarcoma 10, and colorectal cancer 11, suggesting that DDX56 may play a critical role in cancer development and progression." (PMID 36168636, 2022). "Only very recently has it been shown that DDX56 expression is associated with lymphatic invasion and distant metastasis in colorectal cancer, and frequently upregulated in tumor tissues and cell lines of osteosarcoma, suggesting a potential oncogenic role of DDX56 in cancers." (PMID 34446021, 2021). "DDX56 plays an essential role in the progression of multiple cancers, including squamous cell lung carcinoma 8, glioblastoma 9, osteosarcoma 10, and colorectal cancer." (PMID 36168636, 2022). "In addition, knockdown of Ddx56 suspended cell cycle progression from G2M to G1 phase in colorectal cancer cell line." (PMID 32703285, 2020). "In colorectal cancer, six genes were positively correlated: ANLN, ACOT7, OSBPL3, SEC61G, DDX56, and TRIM10." (PMID 40765570, 2025). "One such TCGA screen of candidate genes in colorectal cancer identified that loss of DDX56 reduced intron retention and tumor suppressor WEE1 expression, which functions as a G2-M DNA damage checkpoint, postulating that DDX56 could serve as a potential prognostic biomarker of colorectal cancer." (PMID 34680866, 2021). "Obviously, high expression of the four genes (DDX56, CTSL, ZC3H12D, and PSMC5) could promote the expression of PD-L1 as they have been proven to be promising biomarkers and immunotherapy targets in a variety of tumors, including colorectal cancer, NSCLC, and gastric cancer." (PMID 35647031, 2022).
viral infection (6 papers, 2013 to 2025). "While mammalian DDX56 directly interacts with IRF3 to block its nuclear translocation during viral infection, our study reveals a distinct regulatory mechanism in teleost fish." (PMID 41217109, 2025). "Differentially expressed genes in the viral infection category (174 genes) indicated that keratinocytes had down-regulated genes involved in host gene transcription (DDX56, SMARCA2) and RNA transportation and processing (NUP98, RAE1, XAB2, RBM17, EXOSC10)." (PMID 34552595, 2021). "Given that various members of the DDX family (including, but not limited to, DDX3, DDX5, and DDX56) exhibit distinct regulatory effects on different viral infections, further studies are warranted to determine whether DDX43 exerts a proviral or antiviral effect on other viruses." (PMID 41157636, 2025). "Viral infection is known to impact many aspects of cellular function, and we and others have observed that localization of RNA-binding proteins and nucleolar factors is disrupted during alphavirus infection, including DDX56, nucleolin, NPM1, and fibrillarin (46 and data not shown)." (PMID 33109765, 2020). "Interestingly, we observed neither DDX56 accumulation in the cytoplasm nor nucleolar disruption in cells infected with dengue virus, suggesting that this phenomenon is specific to particular viral infections (data not shown)." (PMID 33109765, 2020).
osteosarcoma (5 papers, 2020 to 2022). A usually aggressive malignant bone-forming mesenchymal neoplasm, predominantly affecting adolescents and young adults. "DDX56, a member of the RNA helicase family, is upregulated in colon adenocarcinoma, lung squamous cell carcinoma, and osteosarcoma." (PMID 36568395, 2022). "In order to validate the gene function of DDX56 in osteosarcoma, knockdown of the expression of DDX56 was performed by introducing a lentivirus cell infection model specifically designed." (PMID 32671031, 2020). "We evaluated the role of DDX56 knockdown in proliferation, cell division, and apoptosis of osteosarcoma cells." (PMID 32671031, 2020). "In conclusion, we have identified DDX56 as a novel oncogene using bioinformatics tools and demonstrated that DDX56 was overexpressed in osteosarcoma tissues and cell lines." (PMID 32671031, 2020). "Furthermore, DDX56 knockdown inhibited cell proliferation and promoted cell apoptosis in osteosarcoma." (PMID 32671031, 2020). "DDX56 expression was measured by RT-qPCR in three osteosarcoma cell lines." (PMID 32671031, 2020). "In the TCGA database, DDX56 is overexpressed in osteosarcoma among other cancers." (PMID 32671031, 2020). "External validation was performed in vitro using several osteosarcoma cell lines to suggest that DDX56 might be a novel oncogene in osteosarcoma." (PMID 32671031, 2020). "We showed that DDX56 was upregulated in the GSE126209 dataset, TCGA SARC patients, and validated using osteosarcoma cell lines." (PMID 32671031, 2020).
squamous cell lung carcinoma (4 papers, 2021 to 2022). A carcinoma arising from squamous bronchial epithelial cells. "DDX56 was published as a functional oncogene which promote the early squamous cell lung cancer recurrence through miRNA modulating Wnt signaling pathway." (PMID 35237592, 2022).
gastric cancer (3 papers, 2022 to 2023). A primary or metastatic malignant neoplasm involving the stomach. "Gain- and loss-of-function studies suggested that DDX56 promotes gastric cancer progression by regulating cell proliferation, apoptosis, invasion and migration functions." (PMID 35723050, 2022).
colon adenocarcinoma (2 papers, 2022). "In addition, the Tumor Immune Estimation Resource (TIMER) database showed that the expression levels of DDX56 mRNA were significantly upregulated in most types of solid tumors, including colon adenocarcinoma, esophageal carcinoma, lung adenocarcinoma, and stomach adenocarcinoma." (PMID 36168636, 2022).
hepatocellular carcinoma (2 papers, 2021 to 2025). A malignant tumor that arises from hepatocytes. "In mammals, DDX56 was found to play a part in cancer processes and had been identified as a potential therapeutic target in hepatocellular carcinoma (HCC) tumorigenesis." (PMID 41217109, 2025).
lymph node metastasis (1 paper, 2022). "The relation of DDX56 expression with clinicopathological features was evaluated, revealing the relation of DDX56 with lymph node metastasis (P < 0.01)." (PMID 35723050, 2022). "The clinicopathological data indicated that the high levels of DDX56 were related to lymph node metastasis." (PMID 35723050, 2022).
infection (11 papers, 2015 to 2025). The state of being infected such as from the introduction of a foreign agent such as serum, vaccine, antigenic substance or organism. "DDX56 has been implicated in both promoting and restricting infection." (PMID 39212449, 2024). "In enterovirus (EMCV) infection, DDX56 directly binds KPNA3/KPNA4, which are critical nuclear import receptors." (PMID 41217109, 2025). "DDX56 plays a role in the innate antiviral immune response and is recruited by viruses such as Went Nile Virus, and infection with WNV results in the relocalisation of DDX56 from the nucleolus to viral assembly sites." (PMID 35769258, 2022). "DDX56 mRNA levels were assessed by real-time PCR at day 5 post-infection with either the DDX56–shRNA or NC lentivirus." (PMID 32671031, 2020). "The West Nile virus capsid biochemically interacts with DDX56 during infection, both in nucleoli and in the cytoplasm, and DDX56 helicase activity is required to promote the packaging of viral RNA into particles." (PMID 32033386, 2020). "We found that DDX56 interaction with the incoming viral genome decreases the stability of viral RNA, preventing this RNA from efficient translation and launching of infection." (PMID 33109765, 2020). "In the cytoplasm, DDX56 impacts the earliest step in the viral replication cycle by binding and destabilizing the incoming viral genomic RNA, thereby attenuating infection." (PMID 33109765, 2020). "While DDX56 is predominantly nucleolar, a fraction is also present in the cytoplasm where viral RNA resides, and cytoplasmic DDX56 levels increase during the early phases of infection." (PMID 33109765, 2020). "It had been proved that overexpression of DDX56 could inhibit virus proliferation, but the expression level of DDX56 decreased significantly at 12 h, especially at 24 h after infection." (PMID 36090064, 2022). "However, accumulation of DDX56 in the cytoplasm over the course of CHIKV infection suggests that as infection proceeds, more DDX56 becomes available for cytoplasmic interaction with viral RNA." (PMID 33109765, 2020). "That DDX56 binds a potentially structured region adjacent to this stem-loop suggests that this region of the genome is of particular importance for regulating early steps of infection." (PMID 33109765, 2020). "We found that DDX56 is dispensable for interferon induction, leading us to hypothesize that DDX56 binds viral RNA to control infection more directly." (PMID 33109765, 2020). "Depletion of DDX56 enhanced infection in Drosophila and human cells." (PMID 33109765, 2020). "Unlike CHIKV-induced cytoplasmic translocation of human DDX56, whose localization affected its activity on CHIKV RNA, gcDDX56 retained nuclear localization throughout infection, suggesting a species-specific regulatory mechanism." (PMID 41217109, 2025).
cancer (10 papers, 2020 to 2025). A tumor composed of atypical neoplastic, often pleomorphic cells that invade other tissues. "Our finding that DDX56 regulates Wnt signaling is intriguing, as aberrant Wnt signaling is frequently observed in cancer and linked to cancer recurrence." (PMID 34446021, 2021). "Some of them are only overexpressed across human cancers, such as DDX27, DDX41 and DDX56, while most of them are both overexpressed and lost in different cancer types." (PMID 36761420, 2022). "Increasing evidence has demonstrated that DEAD-box helicase 56 (DDX56) is over-expressed in several cancers, which plays an oncogenic role." (PMID 35723050, 2022). "Since the Wnt signaling pathway has been shown to play a prominent role in maintaining cancer stemness as well as recurrence after surgical resection, we further investigated the role of DDX56 in the regulation of this pathway." (PMID 34446021, 2021). "Analysis of the functional role of DDX56 in cancer cells revealed that DDX56 modulates expression of multiple Wnt signaling-related genes, promotes growth and migration of SqCLC cells in vitro and xenograft tumor growth in vivo." (PMID 34446021, 2021). "KEGG pathway enrichment analysis performed on both up- and down-regulated mRNAs revealed that the KEGG terms “pathways in cancer” and “Wnt signaling pathway” were significantly enriched in downregulated mRNAs in DDX56 siRNA vs. control siRNA-transfected cells." (PMID 34446021, 2021). "Recent studies targeting DDX56 in cancer is still in its infancy." (PMID 35723050, 2022). "UALCAN was used to determine the protein expression of DDX56 in different types of cancer." (PMID 36568395, 2022). "Our results suggest that DDX56 is a potential pan-cancer biomarker that could be used to predict survival and response to therapy, as well as a potential novel therapeutic target." (PMID 36568395, 2022). "Our results suggested that lower methylation levels of DDX56 DNA may result in high expression levels of DDX56 RNA in some cancers." (PMID 36568395, 2022). "In conclusion, our results clarify the role of DDX56 in the occurrence and development of multiple cancers and provide insight into the molecular mechanisms involved in the process of pathogenesis, indicating a direction for future research on DDX56 in cancers." (PMID 36568395, 2022). "Although DDX56 is reported to be required in virus infection, affecting the response to abiotic stress and host–pathogen interaction, the relationship of DDX RNA helicases with malignancies remains unclear." (PMID 32671031, 2020). "Compared with the diploid, other types (deep deletion and shallow deletion gain amplification) of CNV were significantly correlated with gene expressions of DDX56, ZC3H12D, and PSMC5 (p < 0.05), except for CTSL (p > 0.05), indicating that CNV might regulate the expression of these genes in cancer." (PMID 35647031, 2022). "Therefore, we analyzed pan-cancer single-cell RNA-seq data using the TISCH database and observed that DDX56 was mainly expressed in tumor cells rather than immune cells, stromal cells, and others, indicating the potential of DDX56 as a tumor biomarker and drug target." (PMID 36568395, 2022).
tumor (8 papers, 2016 to 2024). "The results suggested that the expression of DDX56 was associated with immune infiltration in the tumor microenvironment." (PMID 36568395, 2022). "Although previous studies have reported upregulation of DDX56 in several tumor types, the underlying mechanisms of its pro-oncogenic function remain indistinct." (PMID 36568395, 2022). "Furthermore, we found that higher expression of DDX56 was associated with worse patient prognosis in multiple tumor types." (PMID 36568395, 2022). "The results of this study indicate that elevated expression levels of DDX56 in HCC tissues and cells are significantly associated with tumor grades and poor prognoses for HCC patients." (PMID 36168636, 2022). "Here, we report for the first time that the RNA and protein expression levels of DDX56 are significantly higher in tumor tissues than that in control normal tissues in various tumor types." (PMID 36568395, 2022). "Here, we explore the biological functions of DDX56 in 31 solid tumors and clarify that DDX56 can promote oncogenesis and progression in multiple tumor types based on multi-omics data." (PMID 36568395, 2022). "Conversely, DDX56 overexpression significantly increased xenograft tumor volume, tumor weight, and growth." (PMID 36168636, 2022). "According to significant unique analyses (provided by UALCAN, Student’s t-test), DDX56 protein was significantly over-expressed in nine tumor types (p < 0.05)." (PMID 36568395, 2022). "Simultaneously, we observed that the expression levels of CDK9 and DDX56 were both high in THCA tumor tissue (Wilcoxon test, p < 0.05)." (PMID 36568395, 2022). "Consistent with the results which were obtained from the TCGA database, we found that the expression of DDX56 was correlated with tumor size (P = 0.0341), AFP levels (P = 0.0486), and HBV positivity (P = 0.0496);." (PMID 36168636, 2022). "Our results revealed that RNA expression of DDX56 was indeed higher in 16 tumor types, which was confirmed at the protein level in nine tumor types." (PMID 36568395, 2022). "To validate the altered DDX56 protein level as identified by mass spectrometry analysis, we analyzed the DDX56 expression in the same matched tumor tissues from ER and LR SqCLC patients using Western blotting." (PMID 34446021, 2021). "This suggests that TBRG4 may participate in the proliferation and migration of tumor cells through the DDX56/p-AKT/GSK3β signaling pathway." (PMID 38347489, 2024). "Whether DDX56 contributes to tumor progression or could be used as a biomarker remains to be determined." (PMID 36568395, 2022). "Therefore, we provide additional insights into the signaling pathways by which DDX56 promotes tumor proliferation." (PMID 36568395, 2022). "Knockdown of DDX56 suppressed GC growth in the tumor models of BALB/c nude mice." (PMID 35723050, 2022). "This implies that the increased expression of DDX56 is under tumor-specific regulation." (PMID 34446021, 2021). "Finally, we explore the possible mechanisms of high DDX56 expression in tumor tissues." (PMID 36568395, 2022). "Our study showed that the differential expression of DDX56 between ER and matched LR patients was only observed in tumor tissues and not in adjacent normal tissues that exhibited no or weak DDX56 staining by IHC." (PMID 34446021, 2021).
DDX56 also shares sentences with these, for which no sentence is quoted: lung adenocarcinoma (2 papers); brain cancer (1); colon cancer (1); esophageal carcinoma (1); glioblastoma (1); HIV-1 infection (1); Intellectual disability (1); leukemia (1); malaria (1); medulloblastoma (1); melanoma (1); myelodysplastic syndrome (1); oral squamous cell carcinoma (1); ovarian carcinoma (1); rheumatoid arthritis (1); stomach adenocarcinoma (1); systemic lupus erythematosus (1); Usher syndrome type 1B (1); visceral leishmaniasis (1).